HIPK2 (homeodomain interacting protein kinase 2)
Diseases named in the same sentence as HIPK2 in open-access papers (continued):
Sharing a sentence is not in itself a finding about the gene and the disease.
retinoblastoma (1 paper, 2024). A malignant tumor that originates in the nuclear layer of the retina.
Right ventricular hypertrophy (1 paper, 2023). In this case the right ventricle is more muscular than normal, causing a characteristic boot-shaped (coeur-en-sabot) appearance as seen on anterior- posterior chest x-rays. "Furthermore, GLY, 4-PBA and VK3 administration attenuated the increases of RVSP, mPAP and RV/(LV+S), right ventricular hypertrophy, and pulmonary vascular remodeling by targeting on PERK/ATF4/SIAH2/HIPK2 pathway in PAH rats." (PMID 37268944, 2023).
sarcoma (1 paper, 2015). A usually aggressive malignant neoplasm of the soft tissue or bone. "Morphological evaluation of Hematoxylin Eosine (HE)-stained tumor slides showed that both E1A/Ras Hipk2+/+ and −/− MEF-derived tumors were highly malignant sarcomas." (PMID 25868975, 2015).
spinal cord injury (1 paper, 2022). Penetrating and non-penetrating injuries to the spinal cord resulting from traumatic external forces (e.g., WOUNDS, GUNSHOT; WHIPLASH INJURIES; etc.). "In spinal cord injury (SCI), HIPK2 overexpression eases pain by several mechanisms that include inflammatory response." (PMID 36362432, 2022).
thymic carcinoma (1 paper, 2023). Thymic carcinoma (TC) is a type of thymic epithelial neoplasm characterized by a high malignant potential. "Therefore, we investigated the correlation between methylation and mRNA expression status in the genes newly identified as activated or suppressed in thymic carcinomas, specifically HIPK2, HDAC9, NFATC1, PAX9, and SIX1 (the methylation status of FEZF2 was not available in the dataset)." (PMID 38201543, 2023).
thyroid (1 paper, 2019). "Indeed, ~50% of HIPK2/HMGA1 DKO mice display perinatal lethality associated to respiratory distress and thyroid abnormalities." (PMID 31582725, 2019).
tonsil (1 paper, 2017). "As the tonsillar region is the most common location for HPV-associated head and neck SCCs, HIPK2 overexpression in HPV-positive tonsil cancers may be a poor prognostic indicator in a subset of TSCCs, which may develop in individuals who do not consume alcohol." (PMID 28607924, 2017). "To elucidate the involvement of HIPK2 in tonsil cancer, we analyzed HIPK2 mRNA expression levels in 20 normal tonsil and 20 tonsil cancer FFPE samples." (PMID 28607924, 2017).
tonsil cancer (1 paper, 2017). A primary or metastatic malignant neoplasm that affects the tonsil. "HIPK2 overexpression was associated with poorly differentiated tonsil cancer, which is an unfavorable histological factor in patients with TSCC." (PMID 28607924, 2017). "However, these prognostic correlations associated with HIPK2 overexpression were not identified in patients with HPV-negative tonsil cancer." (PMID 28607924, 2017). "Therefore, we focused on aberrant HIPK2 overexpression in tonsil cancer and whether any identified correlations may explain the differences in prognosis or treatment outcome between HPV-positive and HPV-negative TSCC cases." (PMID 28607924, 2017). "HIPK2 overexpression was identified as an independent negative prognostic factor and was associated with decreased OS and DFS in patients with tonsil cancer, specifically in those with HPV-positive TSCC." (PMID 28607924, 2017). "As the efficacy of HIPK2 expression as a prognostic and predictive factor for HPV-positive head and neck cancers is yet to be demonstrated, the present study was performed to address this clinically relevant question in tonsil cancers, stratified by HPV status and postoperative radiation therapy." (PMID 28607924, 2017). "However, the correlations between HIPK2 overexpression and OS or DFS in patients with HPV-negative tonsil cancer were not statistically significant (P = 0.326 and P = 0.345, resp.)." (PMID 28607924, 2017).
tonsillar cancer (1 paper, 2017). "As the majority of patients with tonsillar cancer undergo radiation therapy with or without chemotherapy as a primary treatment, HIPK2 expression could represent a promising tissue marker for the prognosis of patients with TSCC who receive postoperative treatment." (PMID 28607924, 2017).
transitional cell carcinoma (1 paper, 2020). A malignant neoplasm arising from the transitional epithelium, usually affecting the urinary bladder, ureter, or renal pelvis. "In the transitional cell carcinoma lymphatic metastasis, we identified HIPK2 and SEH1 like nucleoporin (SEH1L)." (PMID 32640634, 2020). "Based on betweenness centrality and survival analysis, we identified laminin subunit gamma-2 (LAMC2) in the grade 2 carcinoma, gelsolin (GSN) in the grade 3 carcinoma, and homeodomain-interacting protein kinase 2 (HIPK2) in the transitional cell carcinoma lymphatic metastasis." (PMID 32640634, 2020). "According to the results of the betweenness and survival analysis in four disease types, LAMC2, GSN, and HIPK2 may respectively be the potential regulator in cell lines with grade 2 carcinoma, grade 3 carcinoma, and transitional cell carcinoma lymphatic metastasis." (PMID 32640634, 2020).
urolithiasis (1 paper, 2022). Stone(s) within the urinary tract. "Gene exploration described the association of HIPK2 gene polymorphisms with urolithiasis in males but not in females, and HIPK2 showed a relation to systolic blood pressure, creatinine, and uric acid levels." (PMID 35675329, 2022).
tumor (97 papers, 2008 to 2025). "In these tumors, the downregulation of HIPK2 was associated with poor prognosis, promoted migration, tumor growth, metastasis, or increased cell viability." (PMID 36289359, 2022). "HIPK2 (permutation q-value = 0.001, mutations = 10), a tumor suppressor gene, was found to be involved in two tumor hallmarks." (PMID 30424545, 2018). "Other E3 ubiquitin ligases involved in HIPK2 degradation are induced by hypoxia, a hallmark of tumor progression and failure of tumor therapies." (PMID 27901482, 2017). "Several studies have shown that homeodomain-interacting protein kinase 2 (HIPK2) is an important tumor suppressor involved in HPV-associated uterine cervical and cutaneous carcinogenesis." (PMID 28607924, 2017). "A physiological condition that inhibits HIPK2 functions in solid tumor is hypoxia, a hallmark of tumor progression and failure of tumor therapies." (PMID 22889244, 2012). "Understanding the molecular mechanisms underlying HIPK2 activation and inactivation will therefore give more insight into its role in tumor development and regression." (PMID 22889244, 2012). "A physiological condition that inhibits HIPK2 functions in solid tumor is hypoxia which is a hallmark of tumor progression and failure of tumor therapies." (PMID 21248371, 2011). "The double HIF-1α and HIPK2 knockout greatly counteracted the tumor growth caused by the HIPK2 knockout, suggesting that the effect of HIPK2 depletion on HCC progression was mediated by HIF-1α and by the HIF-1-induced angiogenesis, further strengthening the effect of the HIPK2/HIF-1α balance." (PMID 36900356, 2023). "While the pathways involved in the tumour suppressor role of HIPK2 are relatively well understood, the underlying mechanisms mediating its cytoprotective function(s) remain unclear." (PMID 28692050, 2017). "In addition, high levels of circulating exomiR-1229, associated with HIPK2 downregulation, could be also considered a potential prognostic biomarker in addition to being a potential therapeutic target for inhibiting tumor angiogenesis in CRC." (PMID 36900356, 2023). "In response to oxidative stress, which plays an important role in signal transduction and transcription, HIPK2 maintains its function of facilitating apoptosis and inhibiting tumor growth." (PMID 40004522, 2025). "Homeodomain-interacting protein kinase 2 (HIPK2) has been identified as a potential biomarker for tumor proliferation." (PMID 39995420, 2025). "Though the function of parkin as a tumor suppressor was potentially repressed in the PNS cows, the suppressive actions of HIPK2 on tumor growth as an apoptotic factor was potentially overexpressed." (PMID 40004522, 2025). "Intriguingly, HIPK2 can be the target of miRNAs or hypoxia that inhibit its expression and increase tumor progression or can interact with NRF2 that impairs its apoptotic activity." (PMID 39062921, 2024).
tumor (continued). "Studies have reported that the role of HIPK2 in cancer is complex, with both tumor-suppressive and oncogenic functions, depending on the specific cellular context." (PMID 39598332, 2024). "↓ HIPK2 expression increases the growth of tumor xenografts;Inverse correlation between HIPK2 expression and Dukes stage." (PMID 39062921, 2024). "For instance, fusions of oncogenic proteins TAZ, YAP1, and HIPK2 preserve their tumor-promoting function, while fusions of tumor suppressors, such as NF2, LATS1, FAT1, PTPN14, DCHS2, TAOK1, and TAOK3, results in loss of their function." (PMID 38499647, 2024). "In apparent contrast with our model is the observation of intraindividual reduced levels of HIPK2 mRNA in tumor samples compared to relative para-tumor tissue." (PMID 39342278, 2024). "In particular, HIPK2 inhibition induces a pro-inflammatory phenotype, angiogenesis and cancer-associated fibroblasts (CAF) differentiation, supporting tumor progression and chemoresistance." (PMID 39062921, 2024). "The authors found that the number of HIPK2-positive cancer cells increases with tumor progression and correlates with the TNM stages." (PMID 39062921, 2024). "HIPK2 also plays a role in tumor–host interaction in the tumor microenvironment (TME) by inducing angiogenesis and cancer-associated fibroblast (CAF) differentiation." (PMID 39062921, 2024). "This is in line with previous studies showing that HIPK2 protein downregulation in samples of other cancer types, such as breast, thyroid, and pancreatic, increases tumor progression." (PMID 39062921, 2024). "After this, by knocking out with the CRISPR-Cas9 system the HIF-1α and HIPK2 genes individually or simultaneously, the authors determined the in vivo tumor growth capacities of Hepa1-6 cells in a xenograft mice model." (PMID 36900356, 2023). "Among the tumor-derived exosomes (TEXs), exomiR-1260b has been shown to target HIPK2 in HUVECs and promote angiogenesis, migration, invasion, and chemoresistance of non-small cell lung cancer (NSCLC) cells." (PMID 36900356, 2023). "They observed enhanced in vivo tumor growth of the HIPK2−/− cells while the tumor cells with HIF-1α knockout grew significantly slower compared to the control tumors." (PMID 36900356, 2023). "In this scenario, HIPK2 downregulation by hypoxia-driven mechanisms plays a key role in inducing tumor angiogenesis and solid tumor progression." (PMID 36900356, 2023). "HIPK2 can restrain tumor metastasis by downregulating vimentin, a driver for EMT and tumor invasion." (PMID 36831402, 2023). "Another mechanism that underscores the role of HIPK2 in tumor angiogenesis is the microRNA (miRNAs)-induced HIPK2 modulation." (PMID 36900356, 2023). "Studies performed in animal models showed that HIPK2 overexpression reduces tumor xenografts growth and metastasis formation." (PMID 36900356, 2023). "HIPK2, a multitalented protein, utilizes its kinase activity to regulate several pathways to limit the proliferation and differentiation of tumour cells and induce positive responses to therapies." (PMID 36925653, 2023). "The authors concluded that the CRC-secreted exomiR-1229 can induce tumor angiogenesis by blocking the HIPK2-mediated suppression of VEGF expression." (PMID 36900356, 2023).
tumor (continued). "The studies performed in more than twenty years since its discovery have depicted HIPK2 as a central hub in a molecular network that controls several signaling pathways involved in cell death and proliferation and that restrain tumor growth." (PMID 36900356, 2023). "Homeodomain-interacting protein kinase 2 (HIPK2) is a well-studied tumor suppressor controlling a wide spectrum of biological functions, including hypoxia, cell proliferation, invasion, apoptosis, and the DNA damage response." (PMID 33122827, 2021). "HIPK2 isoform 3 (110 kDa) was the only isoform detected in these tissues—in 12.5% (3/24) of normal tissues and 54.2% (13/24) of tumor tissues." (PMID 33613845, 2021). "Previous studies have shown that HIPK2 inhibits tumor growth by suppressing the angiogenesis through binding to HIF1α and promoting its degradation." (PMID 34963484, 2021). "The administration of CDDP and MTX also significantly decreased the tumor volumes in mice injected with HIPK2-OE cells compared with mice injected with Control-OE cells." (PMID 33613771, 2021). "HIPK2 is a central regulator of life-and-death decisions and potential tumor suppressor in tumor biology." (PMID 34321461, 2021). "RT-qPCR and immunoblotting analysis showed that METTL3 overexpression elevated the expression of miR-221-3p and Che-1 but diminished the expression of HIPK2 in mouse tumor tissues after ADR treatment." (PMID 33420414, 2021). "Hipk2 was shown to be a haploinsufficient tumor suppressor gene in a radiation-induced mouse lymphoma model." (PMID 33613845, 2021). "In patients with NSCLC, the level of HIPK2 was significantly lower in tumor tissues than in normal lung tissues, while that of miR-1260b was higher in tumor tissues." (PMID 34321461, 2021). "We also found downregulation of the expression of TGFB1, a critical molecule involved in cell invasion and tumor metastasis, in HIPK2-OE cells." (PMID 33613771, 2021). "Among the potential target genes, HIPK2 was selected for further validation because of its well-known role in tumor angiogenesis." (PMID 34321461, 2021). "HIPK2 can inhibit several angiogenic genes, including MMP10 and VEGF, to inhibit angiogenesis, while exomi-1229 promotes CRC tumour angiogenesis by inhibiting HIPK2 and inhibiting P-AKT and VEGFA in CRC." (PMID 33865381, 2021). "In summary, this study demonstrated that circASH2L promoted RA-FLS tumor-like behaviors and inflammation via miR-129-5p/HIPK2 axis, extending current knowledge on RA pathogenesis." (PMID 33964939, 2021). "HIPK2 has been reported to be an important tumor suppressor and downregulated in varied malignances." (PMID 33747917, 2021). "Inhibition of miR-221-3p by its specific inhibitor increased the expression of HIPK2 but reduced the expression of Che-1 in mouse tumor tissues after ADR treatment." (PMID 33420414, 2021). "These proapoptotic genes are all the known targets of CtBP1, suggesting that HIPK2 overexpression inhibited tumor growth mainly by inducing the expression of proapoptotic genes." (PMID 33613771, 2021). "In the process of tumorigenesis, HIPK2 functions as a tumor suppressor and its expression is significantly downregulated in several cancer types, such as thyroid carcinomas, skin cancer, and breast cancer." (PMID 33613771, 2021).